PVT1 (Pvt1 oncogene)
Diseases named in the same sentence as PVT1 in open-access papers (continued):
Sharing a sentence is not in itself a finding about the gene and the disease.
cancer (continued). "Many studies have illustrated that PVT1 levels are higher in many cancers with an increased MYC expression than in normal tissues and are associated with a poor prognosis." (PMID 32992461, 2020). "Increases in MYC copy number and PVT1 expression occur in more than 98% of cancer cases with increased 8q24 copy numbers, indicating an interaction between PVT1 and MYC and suggesting that they are part of a common signaling pathway." (PMID 32992461, 2020). "PVT1 and PCAT1, located in the vicinity of the MYC oncogene, are encompassed by the 8q24.21 protein-coding gene desert–a region harboring many cancer risk variants, including CaP risk SNPs in men of African ancestry." (PMID 32059012, 2020). "Identifying and understanding the molecular processes of PVT1 impact on drug resistance will allow for more precise therapeutic interventions in cancer." (PMID 32117705, 2020). "The majority of studies focuses on the linear isoform of PVT1, that promotes cell growth and proliferation in cancer, as well as cell migration, invasion, and drug resistance." (PMID 32228602, 2020). "Even though the amplification of 8q24 has been demonstrated in many studies, pan-cancer analysis of the MYC-PVT1 dysregulation in different cancers yielded a strong correlation between PVT1 and MYC in tumor patients lacking 8q24 locus amplification." (PMID 32117705, 2020). "Potentially, PVT1 can be used in early diagnosis of cancer or for monitoring response to cancer treatment, and chemoresistance." (PMID 32117705, 2020). "The upregulation of PVT1 suggests that it can be used for the early detection of cancer, the prognostication of drug resistance, or as a therapeutic target." (PMID 33076512, 2020). "Its role in cancer is still debated: PVT1 has an oncogenic potential, by stabilizing Myc protein, whereas its promoter functions as a tumor suppressor DNA element that limits Myc oncogene expression and activity." (PMID 32528946, 2020). "PVT1 has been identified to be up-regulated in many tumor tissues and it contributes to the pathophysiology of human cancers." (PMID 32322310, 2020). "Many studies have suggested that there is a positive correlation between the expression level of EZH2 and PVT1 in many types of cancer." (PMID 32117705, 2020). "It has been demonstrated that PVT1 is quantifiable in cancer cells and in serum from cancer patients." (PMID 32117705, 2020). "Upregulation of HAGLROS, PVT1, LINC00160, NEAT1, HCG11, and MCM3AP-AS in cancers were associated with poor clinical outcomes in patients with HCC." (PMID 33050642, 2020). "PVT1 is found to be be upregulated in several type of human cancers, including bladder cancer, hepatocellular carcinoma, cervical cancer, gastric cancer, lung cancer, prostate cancer and OS." (PMID 32021563, 2020). "It has been demonstrated that PVT1 was quantifiable in cancer cells and in serum from cancer patients." (PMID 33329315, 2020). "The oncogenic effects of PVT1 have been demonstrated by studies confirming its amplification/overexpression in many cancers." (PMID 32117705, 2020). "It is of note that although PVT1 has been mostly studied in the context of cancer, this lncRNA is related to multiple and diverse pathologies." (PMID 32083000, 2020). "In this review, we summarize some of the latest findings on PVT1's oncogenic activities, signaling networks and how targeting these networks can be a strategy for cancer therapy." (PMID 32117705, 2020). "The upregulation of PCAT1, PRNCR1, PVT1, and MYC potentially confers the risk of cancer as their upregulation is strongly associated with prostate cancer." (PMID 32680982, 2020). "Many authors have also described the regulation of PVT1 in cancer by genes that suppress tumor growth." (PMID 32117705, 2020).
cancer (continued). "In vitro studies demonstrated that PVT1 expression drives cancer cell proliferation through promotion of the KLF5/BAP1/beta‐catenin signalling pathway." (PMID 32058674, 2020). "Compared with MYC, PVT1 is less studied, but it is involved in critical processes in cancer cells, including DNA rearrangements, genetic instability, microRNA (miRNA) encoding, and also interacts with MYC itself." (PMID 32150871, 2020). "Recent advancements have led to increasing discovery of the critical roles of PVT1 in cancer initiation and progression." (PMID 32117705, 2020). "And we discuss the potential for exploiting these PVT1 regulated mechanisms for therapeutically targeting cancers." (PMID 32117705, 2020). "Plasmacytoma Variant Translocation 1 (PVT1) is a well-known oncogenic lncRNA and has been repeatedly suggested as a novel target in cancer therapy." (PMID 32640630, 2020). "It has been revealed that PVT1 promotes cancer initiation and progression via acting as competing endogenous RNA (ceRNA) or activating STAT3 signaling or KAT2A acetyltransferase or interacting with MYC." (PMID 32021563, 2020). "Upregulation of Pvt1 is detected in numerous cancers, such as melanoma, cervical, gastric, prostate, hepatocellular, esophageal cancers, and AML." (PMID 33133086, 2020). "Expression of PVT1 and FAL1, for instance, associates with advanced TNM stage in different types of cancer." (PMID 33329688, 2020). "Evidence has demonstrated that PVT1 and CCAT1-encoded lncRNAs have oncogenic functions, which is consistent with their higher expression in cancer." (PMID 32127004, 2020). "It has been demonstrated experimentally that insertions or deletions in the PVT1 promoter lead to Myc overexpression and consequently, enhanced growth in cancer cells." (PMID 32083000, 2020). "In particular, we found that the cancer-related lncRNAs PVT1 and MIAT were significantly correlated with CD8 T-cell infiltration in several cancer types." (PMID 32081859, 2020). "The sponging action of PVT1 reduces the number of miRNAs that are able to influence cellular processes, and therefore cancer is able to progress." (PMID 31249809, 2019). "To determine if induction of the cancer phenotype in vitro by PVT1 exon 9 is recapitulated in vivo, we performed experiments with age-matched male NOD SCID γ (NSG) mice." (PMID 31766781, 2019). "In this manner, PVT1 influences the levels of downstream miRNAs, thus regulating the biological behavior of cancer cells." (PMID 31497532, 2019). "Nonetheless, further information is needed to determine the therapeutic value of PVT1 for the treatment of cancers." (PMID 31497532, 2019). "In NSCLC, PVT1 also promotes cancer cell proliferation and cell cycle progression through inhibiting expression of p15 and p21, two growth inhibitors of cell cycle checkpoints." (PMID 31497532, 2019). "In summary, PVT1 will be used for tumor screening, malignant and prognosis evaluating, or even as a molecule target for cancer treatment in the near future." (PMID 31380270, 2019). "Previous studies of PVT1 revealed that there are various mechanisms that contribute to carcinogenesis in cancers." (PMID 31601234, 2019). "Overexpression of copy number of PVT1 has been reported to be involved in multiple types of human cancers, including GC, CRC, BC, OC, bladder cancer, and osteosarcoma." (PMID 31480503, 2019). "The phenotype induced by circPVT1 modulation in cancer cell lines appeared to be independent from its host gene, PVT1. circPVT1 is able to bind miR‐497‐5p by a specific binding site impairing its tumor suppressor activity." (PMID 30719845, 2019). "An increased MYC copy number and PVT1 expression occur in more than 98% of cancer cases with increased 8q24 copy numbers, which points to an interaction between PVT1 and MYC and that they are part of a common signaling pathway." (PMID 31309249, 2019).
cancer (continued). "A positive correlation between PVT1 and patient prognosis has been observed, thus indicating the potential of PVT1 to serve as a prognostic indicator for cancer patients." (PMID 31497532, 2019). "The PVT1 locus in particular is a promising area of study in terms of the discovery of new ceRNA networks in cancer." (PMID 31508377, 2019). "Bioinformatics analyses have identified PVT1 as one of a few key functional lncRNAs in many cancer types." (PMID 31249809, 2019). "PVT1 has been found to be overexpressed in various cancers including breast, lung, colorectal, ovarian, and PCa." (PMID 31766781, 2019). "Numerous studies have provided evidence that PVT1 overexpression is correlated with cancer growth and proliferation both in vitro and in vivo." (PMID 31249809, 2019). "In extracellular fluid, PVT1 mainly promotes cancer initiation, and it normally enhances cellular cancer characteristics in the cytoplasm and cell nucleus." (PMID 31497532, 2019). "Close attention should be paid to the effects of proliferation in future research on PVT1 in cancers." (PMID 31497532, 2019). "Among all dysregulated lncRNAs, PVT1 is well studied and is regarded as an important oncogenic factor in cancer." (PMID 31497532, 2019). "The complex interactions of PVT1, its proximity to the MYC oncogene, and its upregulation in cancer has made PVT1 a gene of significant interest for both screening and therapeutic targeting of cancer." (PMID 31249809, 2019). "These lncRNAs can be either upregulated (e.g., ANRIL, SNHG12, NEAT1 in some cancers, PVT1) or downregulated (e.g., GAS5, NEAT1 in APL) in order to promote cell proliferation and migration, and prevent apoptosis of cancerous cells." (PMID 30654440, 2019). "Several miRNA have been reported to interact directly with PVT1 in different cancers and, importantly, restoration of miRNA levels partially rescues the oncogenic effect of PVT1 overexpression." (PMID 31781490, 2019). "Overall, it seems that PVT1 is a major part of many cascades involved in the dysregulation of cancer cell growth." (PMID 31249809, 2019). "Ultimately, PVT1 is a promising lncRNA that holds promise for potential applications in diverse aspects of cancer healthcare delivery ranging from detection to treatment." (PMID 31249809, 2019). "We summarized multiple mechanisms related to lncRNA PVT1 in cancer cells as the basis of molecular targets and highlighted its potential clinical application value." (PMID 31497532, 2019). "Unexpectedly, they found that when the PVT1 promoter was silenced, tumor cell proliferation was significantly enhanced, which was contrary to the experimental conclusion from previous studies that “PVT1 has a cancer-promoting effect”." (PMID 31309249, 2019). "There is increasing evidence that PVT1 has oncogenic properties and regulates proliferation and growth of many cancers." (PMID 31249809, 2019). "Combining RNA-RNA interaction prediction and transcription regulatory networks, we identified E2F1, FOXM1 and PVT1 regulatory path as recurring pan-cancer regulatory entity." (PMID 30809433, 2019). "The recent characterization of PVT1 CircRNA shows promise for future discovery of biomarkers and drug targets for cancer control." (PMID 31249809, 2019). "Inhibition of the expression of PVT1 in cancer cells reduces the expression of vimentin, while it enhances the expression of E-cadherin." (PMID 31309249, 2019). "Among them, PVT1 is well-studied, and substantial evidence indicates that PVT1 plays critical roles in the onset and development of cancers." (PMID 31497532, 2019). "Further, data from The Cancer Genome Atlas (TCGA) and independent analysis of human clinical tissue samples showed elevated PVT1 expression in cancer tissues in comparison to adjacent normal tissue or matched normal tissue." (PMID 31249809, 2019). "Normally, PVT1 acts as an oncogenic factor by promoting cancer cell proliferation, invasion, metastasis, and drug resistance." (PMID 31497532, 2019).
cancer (continued). "This review summarizes various pathways through which PVT1 regulates the progression of cancer via miRNAs." (PMID 31380270, 2019). "Since the loss of PVT1 expression consistently induced apoptosis and inhibits DNA replication, it is likely that PVT1 regulates the survival, growth, and division of cancer cells." (PMID 31249809, 2019). "In recent reports, PVT1 RNA played an important role in human cancer by regulating the protein stability of important oncogenes, including the c-Myc oncogene." (PMID 31636510, 2019). "On the basis of these mechanisms, PVT1 appears to have a high potential for clinical application in cancer treatment." (PMID 31497532, 2019). "The lncRNA PVT1 has been found to influence the expression of a diverse range of miRNAs in many cancer types." (PMID 31249809, 2019). "PVT1, a long non-coding RNA, has been designated as an oncogene due to its contribution to the phenotype of multiple cancers." (PMID 31877167, 2019). "A circular RNA derived from one exon of the PVT1 gene (known as circ-PVT1) has been reported as a carcinogenic factor in GC, suggesting the oncogenic effect of circ-PVT1 in various cancers." (PMID 31793989, 2019). "PVT1 is an oncogenic lncRNA located at chromosome 8q24.2 downstream of c-Myc, and this region is thought to be cancer-related because of its function with c-Myc and rearrangement." (PMID 31480503, 2019). "According to current understanding, the role of the PVT1-Myc pair is mainly based on the promotion of cancer cell proliferation." (PMID 31497532, 2019). "Multiple meta-analyses have also shown that PVT1 can be used as a new tumor biomarker and a predictor of poor prognosis in different cancers." (PMID 31309249, 2019). "The PVT1 gene, located at locus 8q24, has a close functional relationship with myelocytomatosis (Myc), which exerts oncogenic effects in various cancers." (PMID 31497532, 2019). "Studies have found that PVT1 influences proliferation, invasion, metastasis, drug resistance and angiogenesis in various cancers via the Myc-PVT1 pair, the modulation of miRNAs, and the regulation of gene transcription and protein levels." (PMID 31497532, 2019). "In vivo studies using mouse models have contributed to our understanding of the effects of PVT1 in human cancer." (PMID 31249809, 2019). "In nasopharyngeal cancer, PVT1 promotes cancer stem cell-like traits by downregulating miR-1207 and further induces the activation of the PI3K/AKt cascade." (PMID 31497532, 2019). "The long non-coding RNA PVT1 has repeatedly been shown to promote EMT in various human cancer cell lines." (PMID 31357500, 2019). "It is clear from human tissue and mouse xenograft studies that overall survival and tumor size in many cancer types is related to PVT1 overexpression." (PMID 31249809, 2019). "The up-regulation of PVT1 in tumor tissues can be observed in 18 types of cancers in the TCGA database 32, moreover, several other cohort studies have confirmed this 5, 35-40." (PMID 31598169, 2019). "It is clear that even small circular RNA, such as circPVT1, which has a length of approximately 400 bp and comes from a single exon of the long noncoding PVT1 gene, can bind more than one miRNA and act as a gene expression regulator in cancer." (PMID 30719845, 2019). "Such variation across cancer types underscores the importance of clearly understanding the specific roles of PVT1 overexpression; differences in the effects of PVT1 overexpression in cancer can be seen at the cellular level as well." (PMID 31249809, 2019). "Here, we describe the strong relationship between PVT1 overexpression and cancer progression, and then we discuss the expanding frontiers of PVT1 activity and its potential role in a lncRNA-miRNA-mRNA axis." (PMID 31249809, 2019). "The present meta-analysis aimed to systematically evaluates the metastasis, clinical stage, and prognostic value regarding the expression levels of PVT1 in various cancers." (PMID 30083911, 2019).
cancer (continued). "In order to combine previous research results about PVT1 and cancers to arrive at a summary conclusion, we clarified the relationships between PVT1 expression levels and metastasis, clinical stage or prognosis in cancers in this meta-analysis." (PMID 30083911, 2019). "The dependence of the cancer driving effect of Myc on PVT1 has been observed in the HCT116 cell line (low copy number gain of 8q24), which overexpresses β-catenin, which in turn upregulates the downstream gene-Myc." (PMID 31497532, 2019). "CircPVT1 derives from PVT1 gene, which resides close to MYC in 8q24, identified as a risk locus of many cancers including leukemia." (PMID 31605010, 2019). "Due to the ubiquitous nature of PVT1 upregulation in cancer, there is a need to synthesize the research on its potential utility within the cancer control continuum." (PMID 31249809, 2019). "PVT1 contributes to the overexpression of Myc, thereby inducing the onset and progression of cancer." (PMID 31497532, 2019). "We hope that this review will contribute to a better understanding of the regulatory role of PVT1 in cancer progression, paving the way for the development of PVT1-based therapeutic approaches in cancer treatment." (PMID 31497532, 2019). "We also found that gene fusion of PVT1 with its neighboring gene MYC is most common in 8q24-amplified cancers." (PMID 31309249, 2019). "The number of positive cells was up-regulated by siRNAs, indicating that silencing circ-PVT1 subsequently reduced the survival ability of cancer cells." (PMID 31636510, 2019). "In patients with various types of cancer, a higher PVT1 level indicates a significantly poorer overall survival time, and PVT1 expression is a novel biomarker for cancer diagnosis and prognosis." (PMID 30925926, 2019). "This review has characterized pathways that appear to involve PVT1 in the progression of cancer as well as the development of cancer drug resistance." (PMID 31249809, 2019). "Consistent with the oncogenic role of PVT1 in other cancers, its knockdown reduced proliferation and induced apoptosis in AML cell lines and was accompanied by MYC downregulation in some." (PMID 31338324, 2019). "There have also been some other reports suggesting that PVT1 is related to metastasis in some cancers." (PMID 30679629, 2019). "As far as we know, this is the first meta-analysis providing comprehensive insights into the correlation of PVT1 and cancer clinical stage." (PMID 30083911, 2019). "The analysis of the PVT1 gene in a cohort of 3,769 pediatric cancer samples from the projects PCGP (St." (PMID 31781490, 2019). "LncRNAs such as NEAT1, UCA1, and PVT-1 have been shown to regulate drug resistance in multiple cancer types through different molecular mechanisms." (PMID 35582574, 2019). "As research has progressed, mechanisms utilized by PVT1 to exert regulatory effects on cancers progression have increasingly been identified." (PMID 31497532, 2019). "Because of the upregulated expression of PVT1 in cancers, many studies have predicted and validated its potential for clinical application as diagnostic biomarkers." (PMID 31497532, 2019). "MYC expression has been shown to be highly reliant on PVT1—PVT1 is increased in nearly 98% of cancers displaying overexpression of MYC." (PMID 31508377, 2019). "PVT1 is located downstream of proto-oncogene MYC on chromosomal region 8q24, a known cancer susceptibility locus." (PMID 31508377, 2019). "Above all, the interaction between PVT1 and Myc plays a significant role in cancer initiation and progression, and disruption of this interaction seems to be a potential therapeutic target in cancer treatment." (PMID 31497532, 2019). "Substantial studies have shown that PVT1 can reverse drug-resistance in cancers, and some chemotherapeutic drugs can exert anti-cancer effects through PVT1, such as gemcitabine, carboplatin and docetaxel, paclitaxel, and cisplatin." (PMID 31497532, 2019).